FN1 (fibronectin 1)
Diseases named in the same sentence as FN1 in open-access papers (continued):
Sharing a sentence is not in itself a finding about the gene and the disease.
chordoma (1 paper, 2023). Chordomas are rare malignant tumors arising from embryonic remnants of the notochord in axial skeleton. "This study aimed to clarify the precise function and underlying molecular mechanism of FN1 in chordoma." (PMID 37784253, 2023). "EMT‐like cancer‐associated fibroblasts (eCAFs) had a strong EMT signature in recurrent chordomas, and cancer‐associated fibroblasts (CAFs) expressing fibronectin 1 (FN1) displayed elevated levels of ligands associated with EMT." (PMID 37784253, 2023). "The recurrent chordoma samples expressed FN1 at a higher level than the primary samples, suggesting increased FN1 presence in T cells." (PMID 37784253, 2023). "Initially, we investigated the impact of FN1 on CD4 T cells and CD8 T cells by analysing the presence of CD3D, CD4, CD8 and FN1 in both primary and recurrent chordoma specimens." (PMID 37784253, 2023). "The results suggest that suppressing FN1 can hinder the growth of tumours in mice, providing further evidence of FN1's involvement in promoting chordoma development." (PMID 37784253, 2023). "The expression of FN1 in CD4 T cells, CD8 T cells, macrophages and CAFs was calculated, and FN1 was highly concentrated in recurrent chordomas." (PMID 37784253, 2023). "In summary, these results highlight the essential role of FN1 in the progression of tumours and the suppression of the immune system in chordomas." (PMID 37784253, 2023). "To summarise, our research provides a thorough examination of the transcriptomic and immune characteristics of primary and recurrent chordomas at the single‐cell scale, emphasising the importance of FN1 as a pivotal protein in the recurrence of chordomas." (PMID 37784253, 2023). "The examination uncovered a separate group of chordoma cells that displayed robust FN1 expression concentrated at the forefront of the tumour." (PMID 37784253, 2023). "To further explore the function of FN1 in the regulation of chordoma, we employed a mouse xenograft model." (PMID 37784253, 2023). "The invasion and proliferation of chordoma cells were increased by FN1, and recurrent chordomas showed a higher rate of copy number gain." (PMID 37784253, 2023). "Through CNV analysis, we found that FN1 had a higher frequency of copy number gain in recurrent chordomas, as verified by FISH." (PMID 37784253, 2023). "Fluorescence in situ hybridisation experiments, Transwell assays and xenograft mouse models helped verify the role of fibronectin 1 (FN1) in chordoma." (PMID 37784253, 2023). "Moreover, our study reveals a distinct transformation pattern of FN1 expression from primary chordoma to recurrent chordoma, indicating its significance as a novel therapeutic target in chordoma." (PMID 37784253, 2023). "The results suggest that FN1 may play a role in controlling immune cells and stromal components in the microenvironment of recurrent chordoma." (PMID 37784253, 2023). "This discovery implies that FN1 might have a part in the invasive nature of chordoma cells and their movement within the microenvironment of the tumour." (PMID 37784253, 2023). "Likewise, upregulation of FN1 was observed in macrophages and fibroblasts from recurrent chordoma samples in comparison to primary samples." (PMID 37784253, 2023). "The downregulation of FN1 may further enhance the inhibitory effects on chordoma, making it a promising candidate for targeted treatment." (PMID 37784253, 2023). "Interestingly, in recurrent chordomas, interactions involving FN1 and ITGAV/ITGB1, as well as FN1 and ITGA3/ITGB1, emerged as significant contributors to this communication network." (PMID 37784253, 2023). "In vitro, the migration of chordoma cells was significantly hindered by the knockdown of FN1." (PMID 37784253, 2023). "We found that FN1 was an important factor promoting EMT changes in recurrent chordoma cells." (PMID 37784253, 2023).
chordoma (continued). "Notably, the FN1 pathway showed significant upregulation in recurrent chordoma versus primary chordoma, highlighting its potential role in disease progression." (PMID 37784253, 2023). "Finally, FN1 enhanced the invasion and proliferation of chordomas in vivo and in vitro." (PMID 37784253, 2023). "Consequently, targeting FN1 shows promise as a strategy to inhibit chordoma recurrence." (PMID 37784253, 2023). "Furthermore, we conducted immunofluorescence staining of FN1 and the chordoma marker TBXT." (PMID 37784253, 2023). "Our analysis revealed that the interaction between FN1 and CD44, as well as the interaction between FN1 and ITGA4/ITGB1, plays prominent roles in the communication network of both primary and recurrent chordomas." (PMID 37784253, 2023). "To verify the increased expression of FN1 and TGFB1 in recurrent chordoma, we performed IHC analysis in a separate clinical group, which further confirmed their expression levels in recurrent chordoma." (PMID 37784253, 2023). "FN1 had more CNVs in the recurrent lesions than in the primary lesions, which was confirmed by FISH experiments on the 10 primary and 10 recurrent chordomas." (PMID 37784253, 2023). "Notably, FN1 was increased in tumour cells, CD4 T cells, CD8 T cells, macrophages and CAFs in recurrent chordomas." (PMID 37784253, 2023). "The combined results suggest that FN1 secretion, specifically in CD4 T cells, CD8 T cells, macrophages and fibroblasts, may be increased in the TME of recurrent chordomas." (PMID 37784253, 2023). "Remarkably, FN1 was upregulated, had more CNVs, and was more highly secreted by tumours, macrophages, CD4 T cells, CD8 T cells and fibroblasts in recurrent chordoma than in primary chordoma." (PMID 37784253, 2023).
chronic pancreatitis (1 paper, 2019). A chronic inflammatory process causing damage and fibrosis of the pancreatic parenchyma. "In line with this, mouse models with chronic pancreatitis and PSC in vitro treated with the natural anthraquinone Rhein showed a decreased expression of TGFβ, fibronectin-1, collagen-α1 and Shh." (PMID 31072042, 2019).
Cocaine addiction (1 paper, 2024). "High expression of FN1 enriched in Nicotine addiction, Cocaine addiction, Insulin secretion and Aldosterone−regulated sodium reabsorption." (PMID 38979407, 2024).
Coccidioides infection (1 paper, 2025). "In response to Coccidioides infection, Spp1+ macrophages express high levels of pro-inflammatory (Nos2, Tgfb1, Il1β, and Il6) and fibrotic/wound healing associated genes (Inhba, Spp1, Arg1, Pdgfb, and Fn1)." (PMID 40704794, 2025).
craniosynostosis (1 paper, 2024). Craniosynostosis is defined as the premature fusion of one or more cranial sutures leading to secondary distortion of skull shape resulting in skull deformities with a variable presentation. "Abrogation of Fn1 in cranial mesenchyme leads to insufficient apical extension of FBs and craniosynostosis in CS, suggesting that Fn1 provides migratory guidance for the apical expansion of calvarial osteoprecursors." (PMID 38979034, 2024).
cystic kidneys (1 paper, 2022). "This was associated with an increased mRNA expression of Il1b, Tnf, Mcp1, Fn1, and Col1a2 genes in the cystic kidneys of Pkd1-miR Tg mice." (PMID 35955634, 2022).
diabetic angiopathy (1 paper, 2016). "Increased FN1 expression is one of the main features of diabetic angiopathy." (PMID 27781209, 2016).
ductal breast carcinoma in situ (1 paper, 2023). A carcinoma entirely confined to the mammary ducts. "In a study with ductal breast carcinoma in situ, D’Arcy and coworkers depleted SDC1 in MCF10A cells and observed an upregulation of EMT marker gene expression, including E-cadherin (CDH1), fibronectin-1 (FN1), and claudin-1 (CLDN1)." (PMID 36980680, 2023).
empyema (1 paper, 2022). An accumulation of pus in a body cavity, usually the pleural space. "FN1 deposition was also observed in the thickened pleura of mice having S. pneumoniae-induced empyema." (PMID 35563212, 2022).
Fabry disease (1 paper, 2018). Fabry disease (FD) is a progressive, inherited, multisystemic lysosomal storage disease characterized by specific neurological, cutaneous, renal, cardiovascular, cochleo-vestibular and cerebrovascular manifestations. "In contrast to immortalized human podocytes exposed to lyso-Gb3, expression levels of COL4, FN1, HES1, and TGFβ1 were not elevated in urine-derived cells of Fabry disease patients." (PMID 30038331, 2018).
Female Reproductive Cancers (1 paper, 2026). "The results indicate that two of the studied FN1 gene variants may increase the risk of gynecological cancers in dominant and log-additive models (p = 0.048 and p = 0.040 for rs6725958, p = 0.033 and p = 0.038 for rs1968510, respectively)." (PMID 42196282, 2026).
germ cell tumor (1 paper, 2012). A benign or malignant, gonadal or extragonadal neoplasm that originates from germ cells. "FN1, AXL, and SOX9 demonstrated a similar pattern of expression across all lines and have been shown by others to be over expressed in germ cell tumors." (PMID 22737227, 2012).
goiter (1 paper, 2018). Enlargement of the thyroid gland usually caused by lack of iodine in the diet, hyperthyroidism, or thyroid nodules. "FN1 is an extracellular matrix protein synthesized by fibroblasts, and is often associated with goiters." (PMID 30414611, 2018).
gouty arthritis (1 paper, 2020). "The therapeutic targets through which Simiao decoction alleviated gouty arthritis were p-STAT3, APOB, CASP8, c-FOS, PPARα, FN1, and LPL." (PMID 32670069, 2020).
Headache (1 paper, 2022). Cephalgia, or pain sensed in various parts of the head, not confined to the area of distribution of any nerve. "For example, headache was positively correlated with CA2 and fibronectin 1 (FN1) (ρs > 0.42, p value < 0.05)." (PMID 35668171, 2022).
hemangioma (1 paper, 2025). A benign vascular lesion characterized by the formation of capillary-sized or cavernous vascular channels. "While the high expression of FN1 and collagen may be associated with the regression process of hemangioma." (PMID 41445863, 2025). "By measuring the levels of laminin, FN1 and collagen, it may be possible to assess the progression of hemangiomas." (PMID 41445863, 2025).
hemangiosarcoma (1 paper, 2010). "For example FN-1, which was overexpressed in all hemangiosarcomas evaluated in this set of experiments, is involved in wound healing, blood coagulation, and cancer metastasis." (PMID 21062482, 2010). "The correlation between FN-1 and urokinase is interesting, since the survival rate of patients and dogs with angiosarcoma and hemangiosarcoma, respectively, is exceptionally poor due to its exceedingly high metastatic potential." (PMID 21062482, 2010). "FN-1 expression in hemangiosarcoma samples was estimated to be, on average, 2 fold higher in hemangiosarcomas than in splenic hematomas based on microarray data, and RT-qPCR confirmed expression was increased by 2 to 12 fold." (PMID 21062482, 2010). "The role of urokinase and FN-1 to promote the metastatic phenotype has been the subject of intense study in other tumors, but it remains to be examined in hemangiosarcoma." (PMID 21062482, 2010).
hematoma (1 paper, 2024). A hematoma is a collection of blood from a vascular structure into an extravascular space. "Early wound healing genes (Actb, Postn, Fn1, Tnc) showed higher expression in the one-week interzone as soft tissue repair and hematoma formation resolved." (PMID 38534368, 2024). "Fibronectin 1 (Fn1) was down-regulated in the one-week sample compared to the two-week sample, reflective of hematoma resolution." (PMID 38534368, 2024).
Hematuria (1 paper, 2018). The presence of blood in the urine. "Mutations in CFHR5, a gene playing a role in the regulation of the alternative pathway of complement, in FN1 (fibronectin 1), or in MYH9 (heavy chain of myosin 9), comprise rarer genetic causes of hereditary hematurias." (PMID 29764427, 2018).
HIV-1 infection (1 paper, 2011). The type species of lentivirus and the etiologic agent of acquired immunodeficiency syndrome (AIDS). "Three of these genes baculoviral IAP repeat containing 2 (Birc2), Myc and FN1 are strongly down-regulated, and CDKN2A, CDKN2B and BRAC1 are moderately down-regulated during acute HIV-1 infection." (PMID 21533265, 2011).
Hyperoxaluria (1 paper, 2017). Increased excretion of oxalates in the urine. "Results of our present study show that OPN, MGP, Fetuin B, Fn1, CD 44, Clusterin, Bikunin/AMBP genes are upregulated during hyperoxaluria and further increased with crystal deposition." (PMID 29091707, 2017).
inflammatory breast carcinoma (1 paper, 2022). An advanced, invasive breast adenocarcinoma characterized by the presence of distinct changes in the overlying skin. "In inflammatory breast cancer (IBC), activated T cells could release soluble factors (TNF-α, IL-6, and TGF-β) to facilitate the expression of EMT-related genes, including FN1, VIM, TGM2 and ZEB1, thereby promoting EMT." (PMID 35251963, 2022).
influenza (1 paper, 2022). An acute viral infection of the respiratory tract, occurring in isolated cases, in epidemics, or in pandemics; it is caused by serologically different strains of viruses (influenzaviruses) designated A, B, and C, has a 3-day incubation period, and usually lasts for 3 to 10 days. "Virus-related diseases (SARS-CoV-2 high viral load and influenza) in particular showed significant changes on the expression of lung epithelial-cell-related transcripts (i.e., ACTB, C1R, and FN1); such changes are known markers of lung-injury gene signatures." (PMID 35233546, 2022).
injury (1 paper, 2026). Damage inflicted on the body as the direct or indirect result of an external force, with or without disruption of structural continuity. "Similarly, Fn1 (fibronectin), traditionally linked to extracellular matrix organization, also emerges in coagulation pathways, suggesting it may contribute to clot stabilization and fibrosis during liver injury." (PMID 41598416, 2026).
insomnia (1 paper, 2022). A sleep disorder characterized by difficulty in falling asleep and/or remaining asleep. "In the results, HP, FGA, FGG, FGB, and MMP9 were upregulated in patients with insomnia, and FN1, APP, EGF, AHSG, and IGF1 were downregulated compared with controls." (PMID 35958162, 2022). "The 10 key DEPs screened may be potential targets for insomnia, especially FN1, EGF, HP, and IGF1." (PMID 35958162, 2022).
liposarcoma (1 paper, 2007). A usually painless malignant tumor that arises from adipose tissue. "Genes highly expressed in the dedifferentiated/pleomorphic liposarcomas included cell-cycle genes like CCNA2, CCNB2, CDC2, KIFC1, KIF23 and PTTG1, motility genes like AMFR, ANXA1, CKB, CNN2 and FN1 and homeostasis-related genes." (PMID 17359542, 2007).
liver tumors (1 paper, 2025). "Proteins such as fibronectin (FN1), which is often overexpressed in liver tumors, contribute to the modulation of integrins, adhesion, and cell motility." (PMID 41008923, 2025).
Lynch syndrome (1 paper, 2020). An autosomal dominant hereditary neoplastic syndrome characterized by the development of colorectal carcinoma and a high risk of developing endometrial carcinoma, gastric carcinoma, ovarian carcinoma, renal pelvis carcinoma, and small intestinal carcinoma. "FN1-encoded fibronectin 1 is more highly expressed in the normal rectum than in the normal right colon in patients with Lynch syndrome." (PMID 32824266, 2020).
male infertility (1 paper, 2023). The inability of the male to effect fertilization of an ovum after a specified period of unprotected intercourse. "ALB and FN1 have been suggested as potential biomarkers for oxidative stress in terms of male infertility factors." (PMID 37799407, 2023).
Marfan syndrome (1 paper, 2024). A disorder of the connective tissue. "Marfan syndrome (MFS) is an autosomal dominant connective tissue disorder caused by missense mutations in fibronectin-1 (FBN-1), a component of extracellular microfibrils." (PMID 39402049, 2024).
membrane nephropathy (1 paper, 2025). "The morphologically thin basement membrane nephropathy was associated with a novel gain-of-function mutation in the FN1 gene (c.3415G>A) inherited in an autosomal dominant fashion in the family." (PMID 39859354, 2025).
meningioma (1 paper, 2023). A generally slow growing tumor attached to the dura mater. "The combination of TF and FN1 has been identified as one of the important pair features and showed good classification of meningioma grades." (PMID 37770851, 2023). "Interestingly, a combination of Transferrin (TF) and FN1 along with TF and APOB showed better segregation as serum markers for meningioma grades." (PMID 37770851, 2023).
nasal polyp (1 paper, 2021). "Coagulation proteins FGA, FGB, FGG, and fibronectin (FN1) were all also abundant in nasal polyp biopsies in this study." (PMID 33220024, 2021).
oncocytoma (1 paper, 2010). "In the present study, a significantly increased expression of FN1 mRNA in RCC compared to normal renal tissue and oncocytoma has been shown." (PMID 20860816, 2010).
open-angle glaucoma (1 paper, 2024). Chronic outflow obstruction of the eye's drainage canals that can lead to increased internal eye pressure and optic nerve damage. "Importantly, FN1 is a major player in the development of open angle glaucoma where its accumulation in the trabecular meshwork is believed to contribute to the increase in IOP." (PMID 38272861, 2024).
ovarian serous cystadenocarcinoma (1 paper, 2020). A malignant serous cystic epithelial neoplasm arising from the ovary. "Using The Cancer Genome Atlas (TCGA) ovarian serous cystadenocarcinoma dataset, we found a significant positive correlation (Pearson correlation: 0.63, p = 5.10 × 10−35) between NUAK1 and FN1 mRNA expression in tumours from EOC patients." (PMID 32429240, 2020).
parathyroid adenomas (1 paper, 2024). "Furthermore, ENCODE chromatin state data showed strong transcription in parathyroid adenomas and quiescent chromatin in the non-malignant thyroid gland at the FN1 variant sites." (PMID 39770638, 2024).
pituitary tumor (1 paper, 2022). A benign or malignant neoplasm affecting the pituitary gland. "The gene with the most elevated expression was FN1, which was nearly 100-fold higher in human pituitary tumor tissue than in normal pituitary samples." (PMID 35600354, 2022). "We found that the FN1 transcript level in human pituitary tumors was 3.4 x 104 copies/μg total RNA, which was 89.6-fold (p<0.0001) that observed in normal pituitary tissue and significantly elevated in every tumor type." (PMID 35600354, 2022). "We also determined the expression of fibronectin 1 (FN1) in pituitary tumor tissue." (PMID 35600354, 2022).
Pneumocystis infection (1 paper, 2010). "Among the genes that were affected by dexamethasone and further affected by Pneumocystis infection, Mgst1 and Hspa1b genes were down-regulated, while Cd14, Irf8, Il1b, Cxcl13, Cxcr4, Fn1, Irf1, Cd74, S100a9, and Spp1 genes were up-regulated in all four groups." (PMID 20377877, 2010).
protozoal infections (1 paper, 2023). "Notably, ICAM1, TLR2, and FN1 were associated with bacterial, viral, and protozoal infections, a conclusion also observed in numerous additional studies." (PMID 37233676, 2023).
pseudoexfoliation glaucoma (1 paper, 2022). "It has been proved that FN1 was upregulated in tears, tenon's capsule and aqueous humor samples in pseudoexfoliation glaucoma, and that inhibiting FN1 would promote the proliferation and invasion of TM cells." (PMID 35461232, 2022).
Renal atrophy (1 paper, 2023). Atrophy of the kidney. "Previous studies have identified MMP9 as a DEG in IF/TA patients, and Fn1 was identified as a DEG in a study employing an animal model of renal atrophy or allograft damage." (PMID 37623492, 2023).